CDKN2A (cyclin dependent kinase inhibitor 2A)
Diseases named in the same sentence as CDKN2A in open-access papers (continued):
Sharing a sentence is not in itself a finding about the gene and the disease.
glioma (continued). "In the case of grades 3 and 4 gliomas, the presence of CDKN2A mutations represents an independent risk factor, in terms of low survival and poor prognosis, but the same was not highlighted in low-grade gliomas." (PMID 36290853, 2022). "In addition, by analyzing TCGA cohort mRNA expression data, we also found that FDX1 and CDKN2A were upregulated in WHO 2/3 glioma tissues." (PMID 36059638, 2022). "We performed receiver operating characteristic curve (ROC) analyses to assess whether various CRG levels aided glioma detection; the areas under the curves (AUCs) were >0.9 for CDKN2A, FDX1, DLD, and PDHB." (PMID 36579333, 2022). "Moreover, the CDKN2A/MTAP deletion is mostly observed in higher grade glioma and hence tumors at early stage cannot be treated by solely targeting MTAP loss." (PMID 36572880, 2022). "The CDKN2A mutants clustered imperfectly when using the panels and these associations are weaker than the very strong correlations between IDH and BRAFV600E mutations and CIMP status in glioma and CRC, respectively." (PMID 35260776, 2022). "Thus, we can associate the importance of its role in the prognosis of glioblastomas IDH-wild type with that of the CDKN2A gene in IDH-mutant gliomas." (PMID 36547116, 2022). "Besides these, we noted the association of necrosis with the altered status of the CDKN2A gene, an aspect also noted by other researchers but in cases of IDH-mutant gliomas." (PMID 36547116, 2022). "To validate the CDKN2A ddPCR assay in glioma tissue samples, we investigated 66 gliomas of different types with known CDKN2A copy number status determined by NGS and/or a TaqManTM copy number assay with the reference gene RPPH1, including 10 cases with homozygous CDKN2A deletion." (PMID 35361262, 2022). "CDKN2A/B status was available in only 118 of the 168 IDH-mut gliomas." (PMID 35083156, 2021). "Recently, it has been shown that CDKN2A homozygous deletion was associated with poorer outcome among IDH-mutant gliomas lacking 1p/19q codeletion (IDH-mutant astrocytoma) as well as among anaplastic oligodendrogliomas, IDH-mutant-1p/19q codeleted." (PMID 34496929, 2021). "Furthermore, BRAF p.V600E mutation is frequently associated with additional SNVs, including homozygous CDKN2A deletions, that carry the risk of transforming a PLGNT to a higher-grade glioma, specifically in PXAs." (PMID 33779771, 2021). "Finally, we validated the genetic connections and the prognostic significance of EGFR and CDKN2A alterations using the MSKCC glioma datasets." (PMID 33959491, 2021). "Finally, the coexistence and unfavorable prognostic effects of EGFR amplification and CDKN2A alteration were validated using the Memorial Sloan Kettering Cancer Center (MSKCC) glioma datasets." (PMID 33959491, 2021). "Here, we revealed the co-occurrence of EGFR amplification and CDKN2A deletion in patients with glioma, suggesting that the poor drug response of EGFR inhibitors in glioma may be associated with CDKN2A deletion." (PMID 33959491, 2021). "Although 9p losses can be found in many gliomas, they more commonly occur in higher grade tumors (grades 3 and 4), which make the CDKN2A gene or p16 protein (CDKN2A product) potential players involved in the malignant progression and anaplastic transformation of low-grade gliomas into higher grades." (PMID 34675774, 2021). "Non-codeleted gliomas showed distinct proportions of a key genomic aberration (CDKN2A/B loss) among immune cell-based groups." (PMID 34496929, 2021). "In contrast to adult low-grade gliomas, PLGNTs do not commonly lose CDKN2A expression, with an incidence of loss of 6–20% in PLGNTs." (PMID 33779771, 2021).
glioma (continued). "Interestingly, a study on gliomas arising in neurofibromatosis 1 (NF1) found the same frequent CDKN2A and ATRX genetic alterations in NF1 high-grade gliomas." (PMID 31677015, 2020). "Furthermore, amplification peaks of oncogenes (PIK3C2B, PDGFRA, EGFR, CDK4), and deletion peaks of tumor suppressor genes (TUSC1, CDKN2A, CDKN2B, PTEN, FAS, BNIP3) were detected in the gliomas with a high risk score." (PMID 32023222, 2020). "Our results revealed that GBMs have the highest occurrence of CDKN2A gene deletion among gliomas." (PMID 32516884, 2020). "In line with CDKN2A loss-of-function and consecutive activation of the cyclin D1/cyclin dependent kinase (CDK) 4/6 complex, Rb was hyperphosphorylated in the majority of double-mutant glioma cells, indicating functional inhibition." (PMID 31391125, 2019). "Some studies have shown that co-deletion of CDKN2A and MTAP could be used as markers for glioma stratification, and the deletion of CDKN2A was associated with the expression of CDK4/6 in various tumors." (PMID 31719831, 2019). "Further more, the loss of p16 has been reported in some anaplastic PA, and a recent study involving 73 anaplastic astrocytomas with pilocytic features found that these gliomas are characterized by frequent MAPK pathway alterations, CDKN2A/B deletion, ATRX loss, and unfavorable prognosis." (PMID 29983406, 2019). "Indeed, astrocytes with a homozygous deletion of CDKN2A/B can grow indefinitely in culture, and introduction of p16INK4a in immortal human glioma cell lines with this deletion leads to cell cycle arrest and senescence." (PMID 29616301, 2018). "Previous analyses of IDH mutated and 1p/19q codeleted gliomas suggest that protein p16 loss is not a consequence of deletion or mutation of the CDKN2A gene—as found in glioblastomas —but rather to epigenetic changes or impaired protein synthesis." (PMID 29489901, 2018). "In these patients with secondary high-grade gliomas the most recurrent genetic alterations were BRAFV600E mutation and CDKN2A deletion: in the large majority of cases these mutations could be traced back to the corresponding low-grade glioma." (PMID 30279357, 2018). "Another tumor suppressor gene, CDKN2A, encoding two proteins p14ARF and p16INK4a, has also been reported to be associated with the development of several cancers, such as HNSCC, cervical neoplasia and glioma." (PMID 28445979, 2017). "A subsequent study reported that the BRAFV600E mutation and CDKN2A deletion are more frequent in pediatric low-grade glioma that transform to high-grade malignancy than in non-transforming tumors." (PMID 27713119, 2016). "To test whether BrafV600E cooperates with Cdkn2a (Ink4a-Arf) deletion to induce glioma formation, we injected Ad-cre near the SVZ of adult BrafCA/+ and BrafCA/+Ink4a-arffl/fl mice, respectively." (PMID 27713119, 2016). "Cumulatively, the results of mutation screening studies indicate that BRAFV600E is important to multiple pediatric glioma types, and suggest that this oncogenic alteration cooperates with CDKN2A deletion to promote neoplastic transformation and tumor malignant progression." (PMID 27713119, 2016). "Besides reporting a high frequency of TERT promoter mutations in different glioma types, we describe the correlations with IDH mutations and deletions at 1p, 19q and CDKN2A/B loci that have prognostic implications." (PMID 25797251, 2015).
glioma (continued). "Tumor suppressor genes that are more often associated with glioma progression, CDKN2A (9p) and PTEN (10q), were also not mutated in either the primary tumor or the xenograft." (PMID 23527265, 2013). "However, flavopiridola, an available cyclin D1 inhibitor reserved the accelerated cell growth and the increased phosphorylation of pBb induced by CDKN2A knockdown in low-grade glioma cells." (PMID 21843312, 2011). "Overexpression and knockdown of CDKN2A were performed in human glioma cell lines." (PMID 21843312, 2011). "CDKN2A potently inhibited colony-forming activity in various glioma cell lines." (PMID 21843312, 2011). "The expression of Cylin D1 reversely correlates with CDKN2A expression in patients glioma tissues." (PMID 21843312, 2011). "Decreased CDKN2A in high-grade glioma indicated that CDKN2A may be involved in malignant glioma carcinogenesis." (PMID 21843312, 2011). "Moreover, overexpression of CDKN2A inhibits growth of glioma cell lines by suppression of cyclin D1 gene expression." (PMID 21843312, 2011). "Additionally, high RCAN1-4 expression was noted in adult gliomas with malignant molecular characteristics and was associated with the induction of specific mutations in GBM organoids, such as CDKN2A/B codeletion and EGFRvIII." (PMID 41436600, 2026). "In addition, PCNSHS and glioma may also show overlapping molecular features, such as BRAF V600E mutation or BRAF gene fusion, CDKN2A/CDKN2B homozygous deletion, etc." (PMID 40231251, 2025). "In the remaining cases, information on CDKN2A/B status was missing in 40 patients with IDH-mutant astrocytoma, and information on molecular features of glioblastoma (TERT mutation, EGFR amplification, 7p + /10q-) was missing in 27 patients with IDH-wildtype glioma." (PMID 39954095, 2025). "Furthermore, as proof-of-concept, we studied whether DMS could further characterize IDH mutant gliomas of genetic prognostic markers 1p/19q codeletion and CDKN2A/B homozygous deletion status using PGOs." (PMID 39578301, 2025). "Piloid features in a setting of high-grade glioma may harbor ATRX mutation and CDKN2A deletion." (PMID 40277798, 2025). "Both CDKN2A gene products, p14 and p16, can inhibit angiogenesis in glioma cells by upregulating tissue inhibitor of metalloproteinase‐3 or downregulating vascular endothelial growth factor, respectively, indicating that the loss of CDKN2A may promote blood vessel growth in vivo." (PMID 40264576, 2025). "In addition, a recent large-scale WGS study using a total of 156 recurrent gliomas arising in patients after radiotherapy found small deletion burden and homozygous deletion of CDKN2A as biomarkers of short survival and recurrence after radiotherapy, respectively." (PMID 41007286, 2025). "Therefore, confirming CDKN2A/B status is essential in gliomas with IDH-mutant and wild-type pTERT." (PMID 38473369, 2024). "Interestingly, our study showed that CDKN2A homozygous deletion played a significant role as a negative prognostic factor in CNS WHO grade 4 glioma patients, regardless of the IDH mutation status." (PMID 39457569, 2024).
glioma (continued). "Some molecular markers, such as IDH, 1p/19q codeletion, EGFR amplification, CDKN2A/B loss, and TERT promoter mutation, etc. have been routinely tested in clinical practice and cooperated with histopathological information to form the classification scheme of glioma." (PMID 39906742, 2024). "Furthermore, only a minority of such research has specifically examined imaging features associated with CDKN2A/B status in IDH-mutant astrocytomas that would otherwise be considered grades 2–3, which is the group of gliomas for which CDKN2A/B is most relevant according to the 2021 classification." (PMID 37316586, 2023). "Therefore, CDKN2A/B has been included in the molecular diagnosis of gliomas." (PMID 35711921, 2022). "Also, the WHO CNS5 classifies tumors with alterations in H3F3A to the pediatric-type diffuse high grade gliomas family as they have significantly worse outcomes, and tumors with homozygous CDKN2A/B deletion as having the highest malignancy grade in the group of diffuse, IDH-mutant astrocytomas." (PMID 36425564, 2022). "According to the analysis in regard to distinct molecular markers, we found that the mRNA expression signature was significantly elevated in IDH wildtype tumors, cases without 1p/19q codeletion, gliomas with homozygous loss of CDKN2A/B and in the EGFR amplification group." (PMID 36187350, 2022). "Also, the prognostic effects of SPATS2L in glioma and the associations between SPATS2L and EGFR and CDKN2A alterations are unknown." (PMID 33959491, 2021). "Interestingly, glioma induction with the kRas and Akt3 combination required CDKN2A deletion." (PMID 26993778, 2016). "To establish a tumor-derived glioma cell line carrying the BrafV600E mutation and deficient for Cdkn2a, we injected adenovirus expressing cre recombinase (Ad-cre) into the corpus callosum of ten week-old, cre-conditional, FVB/N BrafCA/+Ink4a/ArfLoxP/LoxP (fl/fl)transgenic mice." (PMID 27713119, 2016). "Within IDHwt gliomas, the significant CNAs observed in lower grade and GBM tumors were generally very similar, including gain of entire copies of chromosome 7, loss of entire copies of chromosome 10, and focal losses at chromosome 9 around the CDKN2A/CDKN2B locus." (PMID 26091668, 2015). "MTAP deficiency may occur without the loss of adjoining CDKN2A in non-small cell lung cancers and gliomas." (PMID 25426549, 2014). "Moreover, hyperexpression of ID4 was found to be a key regulator of malignant transformation of Ink4a/Arf −/− (cyclin-dependent kinase inhibitor 2A, isoform 4) murine astrocytes in in vivo experiments, resulting in formation of high grade gliomas according to clinical and histological analysis." (PMID 23613880, 2013).
glioma (continued). "There are three published GWAS to date that have identified eight different loci associated with glioma risk, including variants annotating key genes in glioma progression, such as the epidermal growth factor receptor (EGFR), and the tumor suppressor gene CDKN2A (alias p14, p16, and ARF)." (PMID 23236348, 2012). "However, knockdown of CDKN2A promotes the low grade gliomas to high grade gliomas." (PMID 21843312, 2011). "According to previous research, WES achieves 30% to 40% higher detection rates for CDKN2A/B homozygous deletions and FGFR-TACC fusions compared to targeted sequencing, and these alterations serve as critical markers for revising glioma grades." (PMID 41377022, 2025). "According to the WHO 2021 Classification of Gliomas, EGFR amplification and CDKN2A/B HD play crucial roles in integrated malignancy diagnosis." (PMID 40786409, 2025). "Regarding CDKN2A, a gene altered in a wide array of gliomas, structural alterations are rarely found in H3K27-altered gliomas." (PMID 39126064, 2024). "We successfully modeled the rebound growth of pediatric glioma upon MAPKi withdrawal in vitro using BT-40 (BRAFV600E, CDKN2A/Bdel)." (PMID 38630384, 2024). "Homozygous deletion of CDKN2A/B is known to be a common gene alteration in GBM, but subsequent analysis has shown that it is a characteristic of IDH-mutant gliomas, especially astrocytomas." (PMID 38473369, 2024). "In multivariate analyses, CDKN2A homozygous deletion was a predictor of significantly shorter PFS and OS in low-grade glioma and glioblastoma across all included studies." (PMID 39457569, 2024). "In this subgroup analysis, even patients with IDH1/2 mutation (Group B), previously known as a better prognostic factor for glioma, had shorter PFS and OS than patients with the IDH1/2 wildtype if accompanied by CDKN2A deletion (Group C)." (PMID 39457569, 2024). "The WHO classification of central nervous system tumors (5th edition) classified astrocytoma, IDH-mutant accompanied with CDKN2A/B homozygous deletion as WHO grade 4." (PMID 39117984, 2024). "They described a Japanese cohort of 308 low-grade gliomas that were comprehensively profiled for glioma-relevant genes via WES and CDKN2A/B via SNP array." (PMID 37504251, 2023). "Of the 23 cases with deletion of CDKN2A, 5 had heterozygous deletions, and all of those were present in the H3G34-mutant gliomas." (PMID 37524847, 2023). "The expression of GLS (p < 0.001), LIPT1, FDX1, SLC31A1 (p < 0.01), DLST, CDKN2A, PDHA1, ATP7A, ATP7B, and NFE2L2 (p < 0.05) was different between glioma and adjacent tissues." (PMID 36936439, 2023). "Regarding the CDKN2A FISH results, homozygous deletions were mostly found in IDH-wt GBM, IDH-mutant 1p/19q OG (grade 3), and H3K27-altered gliomas." (PMID 36900302, 2023). "This variability is only partly accounted for by new additions in WHO 2021 such as the presence of CDKN2A/B homozygous deletion for IDH-mutant astrocytomas and additional molecular features of glioblastoma for IDH-wildtype gliomas." (PMID 37316586, 2023). "Our results showed that risk subclonal mutation correlated with the deletion of 9p21.3 (which contained CDKN2A and CDKN2B) in gliomas, especially in LGG." (PMID 35496054, 2022).